APOD (apolipoprotein D)
Diseases named in the same sentence as APOD in open-access papers (continued):
Sharing a sentence is not in itself a finding about the gene and the disease.
Cachexia (1 paper, 2019). Severe weight loss, wasting of muscle, loss of appetite, and general debility related to a chronic disease. "Based on the fact that circulating levels of tumor-derived factors were correlated with cachexia development and predicted outcome in cancer, we also investigated the predictive potential of seven transcripts (NCAM1, CNTN1, SCG2, CADM1, IL-8, NPTX1, and APOD)." (PMID 31455042, 2019).
cardiomyopathy (1 paper, 2023). A disease of the heart muscle or myocardium proper. "Based on gene expression and histology, clusters 0, 2, and 4 are skeletal muscle due to the high expression of APOD, MB, TCAP, and TNNC2 with significant upregulation of contractile components and cardiomyopathy processes." (PMID 37370820, 2023).
cataract (1 paper, 2021). Partial or complete opacity of the crystalline lens of one or both eyes that decreases visual acuity and eventually results in blindness. "Conversely, female POAG patients had significantly greater levels of APOA1 (FC = 1.36; p < 0.01), APOA2 (FC = 1.21; p = 0.03), APOA4 (FC = 1.30; p = 0.04), APOC3 (FC = 1.38; p = 0.01), and APOD (FC = 1.20; p = 0.04) compared to cataract patients." (PMID 34602085, 2021).
cocaine dependence (1 paper, 2024). A psychologically and socially impaired state, with or without physiological changes, that develops as a result of using cocaine and which leads to compulsive behaviors to acquire the substance. "We also observed a negative correlation between ROS/RNS and age of alcohol use onset (rho = −0.360, p = 0.039) and positive correlations between ApoD and alcohol abstinence duration (rho = 0.411, p = 0.023) and between ApoD and cocaine dependence onset (rho = 0.503, p = 0.048)." (PMID 38535924, 2024).
cold (1 paper, 2023). "APOD is included in a novel necrosis-related gene model for predicting the prognosis of gastric adenocarcinoma and is closely associated with the immune microenvironment of cold tumors." (PMID 37180146, 2023).
epilepsy (1 paper, 2024). A brain disorder characterized by episodes of abnormally increased neuronal discharge resulting in transient episodes of sensory or motor neurological dysfunction, or psychic dysfunction. "A selective increase in APOD mRNA was observed in hippocampal tissues in a kainic model of epilepsy in rats." (PMID 39063177, 2024).
glioblastoma (1 paper, 2022). The most malignant astrocytic tumor (WHO grade IV). "ApoD and BSG co-labelling is also observed in U87 glioblastoma cells." (PMID 35460054, 2022).
heart failure (1 paper, 2024). Inability of the heart to pump blood at an adequate rate to meet tissue metabolic requirements. "Circulating apoD levels have been observed to be increased in heart failure patients, and apoD plays an important role in inflammation." (PMID 38339027, 2024).
hyperlipidemia (1 paper, 2018). "The increase in the plasmatic levels of ApoD in PD is significant even in the presence of comorbidities, potentially compromising the lipid homeostasis as, for example, in hyperlipidemia." (PMID 29780571, 2018).
injury (1 paper, 2014). Damage inflicted on the body as the direct or indirect result of an external force, with or without disruption of structural continuity. "ApoD, the protein product, has been demonstrated to exert neuroprotective and neurotrophic effects in cell culture and in a rodent model of excitotoxic brain injury." (PMID 24558408, 2014).
ischemic stroke (1 paper, 2014). A stroke disorder caused by obstruction of blood flow to the brain, due to thrombotic (local blood clot formation) or embolic (due to a blood clot or other material traveling from another site) event. "We conclude that the SNP rs7659 within the APOD gene might be related to risk and severity of ischemic stroke in patients." (PMID 25261976, 2014).
keloid (1 paper, 2025). An irregularly shaped, elevated mark on the skin caused by deposits of excessive amounts of collagen during wound healing. "Results showed a higher proportion of IGFBP2+/APOD+ cells in normal skin samples compared to the keloid group." (PMID 39902627, 2025). "IGFBP2+ fibs are distinguished by the expression of marker genes including IGFBP2, FGFBP2, OLFML2A, CPE, APOD, and SLC7A2, which are markedly upregulated in normal skin tissue relative to keloid tissue." (PMID 39902627, 2025). "We then focused on comparing the expression differences of IGFBP2+ fib marker genes (IGFBP2, FGFBP2, OLFML2A, CPE, APOD, SLC7A2) between keloids and normal controls." (PMID 39902627, 2025).
kidney failure (1 paper, 2020). An acute or chronic condition that is characterized by the inability of the kidneys to adequately filter the blood. "In the present investigation, apoD was related for the first time to markers of kidney failure (including urea, creatinine, and eGFR)." (PMID 32921312, 2020).
lymphoma (1 paper, 2025). A malignant (clonal) proliferation of B- lymphocytes or T- lymphocytes which involves the lymph nodes, bone marrow and/or extranodal sites. "APOD was also used as a potential marker for dexamethasone treatment of lymphoma." (PMID 40989158, 2025).
Niemann-Pick disease (1 paper, 2017). A group of inherited, severe metabolic disorders in which sphingomyelin accumulates in lysosomes in cells. "In human Niemann–Pick disease, cholesterol and/or sphingolipids accumulate in late endosomes/lysosomes due to mutations in the intracellular cholesterol transport proteins NPC1 or NPC227, and is accompanied by an increase in Apolipoprotein D expression." (PMID 28904344, 2017).
Niemann-Pick disease type A (1 paper, 2023). Niemann-Pick disease type A is a very severe subtype of Niemann-Pick disease, an autosomal recessive lysosomal disease, and is characterized clinically by onset in infancy or early childhood with failure to thrive, hepatosplenomegaly, and rapidly progressive neurodegenerative disorders. "This can lead to dysfunctional macromolecule turnover, be it lipids, proteins or others, as observed in lysosomal storage diseases, some of which ApoD is involved in (Niemann–Pick disease type A and C)." (PMID 37237893, 2023). "Furthermore, ApoD seems to be necessary to mitigate lysosome alkalinization (and regain of adequate pH after alkalinization) and reduce membrane permeability upon paraquat (PQ) injury in a Niemann–Pick disease type A model." (PMID 37237893, 2023).
osteosarcoma (1 paper, 2024). A usually aggressive malignant bone-forming mesenchymal neoplasm, predominantly affecting adolescents and young adults. "In addition, APOD induced the osteoblastic differentiation of the osteosarcoma cell line Sao-2." (PMID 38212768, 2024).
pituitary adenomas (1 paper, 2023). "The expression levels of ANXA2, PMAIP1, SPRY2, C2CD4A, APOD, FGF14 and FKBP10 were significantly upregulated while FNDC5 and MAP3K4 were downregulated in the invasive gonadotrophic pituitary adenomas compared to the non-invasive ones." (PMID 36750863, 2023).
psoriasis (1 paper, 2025). An autoimmune condition characterized by red, well-delineated plaques with silvery scales that are usually on the extensor surfaces and scalp. "The aim of this study was to evaluate the potential associations between serum concentrations of apolipoproteins (ApoA1, ApoA2, ApoB, ApoC1, ApoC3, ApoD, ApoE, ApoH, and ApoJ) and various clinical and biochemical markers in patients with psoriasis." (PMID 40137160, 2025). "While limited prior research has primarily focused on apolipoproteins such as ApoA1, ApoA2, ApoB, ApoC1, ApoC3, and ApoE in psoriasis, our study uniquely extends this scope by also evaluating ApoD, ApoH, and ApoJ in this patient population for the first time." (PMID 40137160, 2025). "Significantly higher concentrations of serum ApoD in severe psoriasis than in mild disease in the present study may have a similar meaning." (PMID 40137160, 2025). "While ApoA1 and ApoB in psoriasis have been the primary focus of research due to their established roles in lipid metabolism and cardiovascular risk, other apolipoproteins, such as ApoA2, ApoC1, ApoC3, ApoD, ApoE, ApoH, and ApoJ, have not been widely studied in psoriasis." (PMID 40137160, 2025).
sarcopenia (1 paper, 2026). Progressive decline in muscle mass due to aging which results in decreased functional capacity of muscles. "The specific elevation of serum APOD protein was subsequently confirmed through orthogonal validation via ELISA in an independent cohort, where its levels were significantly higher in patients with early sarcopenia compared to healthy controls." (PMID 42004707, 2026).
SARS-CoV infection (1 paper, 2023). "ApoD is highly expressed in the lung and has been shown to be increased in patients with chronic obstructive pulmonary disorder as well as in the lungs of mice during SARS-CoV infection." (PMID 37343697, 2023).
Sepsis (1 paper, 2020). Sepsis is defined as life-threatening organ dysfunction caused by a dysregulated host response to infection. "Similar to the reduced level of ApoA1 and A2 reported in sepsis, plasma levels of ApoC2, C3, and ApoD decreased with increasing NEC severity." (PMID 33133078, 2020).
synovial sarcoma (1 paper, 2020). "Representative downstream genes in the SNF5 pathway, Sox2 and ApoD, were significantly upregulated in eMCs expressing SS18-SSX1 and also in mouse synovial sarcomas." (PMID 32019274, 2020).
temporal lobe epilepsy (1 paper, 2024). A localization-related (focal) form of epilepsy characterized by recurrent seizures that arise from foci within the temporal lobe, most commonly from its mesial aspect. "Several apolipoproteins (APOA1, APOD, and APOA4), serpin protease inhibitors (SERPINA3, SERPINF1, etc.), complement components (C9, C8, and C1R), and a total of 42 proteins were found to be significantly upregulated in the temporal lobe epilepsy group." (PMID 39063177, 2024).
thalassemia (1 paper, 2019). An inherited blood disorder characterized by a decreased synthesis of one of the polypeptide chains that form hemoglobin. "However, there are very limited reports regarding the functions of APOD in hematopoiesis, and especially in thalassemia." (PMID 30813444, 2019). "However, the associated function of APOD with these signaling molecules, including AKT, JNK, and FOXO3, has not been studied in thalassemia." (PMID 30813444, 2019).
thyroid autoimmunity (1 paper, 2025). "From a proteomic perspective, differential expression of proteins such as apolipoprotein D (APOD), paraoxonase 1 (PON1), and heparan sulfate proteoglycans in FF has been shown to predict adverse pregnancy outcomes in subgroups including women with thyroid autoimmunity." (PMID 41226407, 2025).
transmissible spongiform encephalopathies (1 paper, 2011). "Several studies have also reported the involvement of many members of the apolipoprotein gene family (ApoA1, ApoA4, ApoC1, ApoC2, ApoC3 and ApoD) in transmissible spongiform encephalopathies." (PMID 21629698, 2011).
urinary bladder carcinoma (1 paper, 2014). "For this we used the urinary bladder carcinoma cell line T24, which produces apoD and displays contact inhibition when cultured in vitro, which has previously been shown to affect apoD production." (PMID 25513803, 2014). "Furthermore, we found that apoD increases the binding of HDL to actively growing T24 bladder carcinoma cells but not to quiescent, contact-inhibited, confluent T24 cells." (PMID 25513803, 2014).
tumor (47 papers, 2010 to 2026). "CYP1B1 and APOD have already been associated with tumor pathobiology in the literature, and their roles in various cancers are explored below." (PMID 40989158, 2025). "Further analysis revealed that APOD, STC1, F2R, and AGT genes are mainly expressed in tumor-associated fibroblasts." (PMID 40677704, 2025). "The first niche, predominantly observed in patients responding positively to immunochemotherapy, is characterized by the notable presence of SELP+ HEV-like vessels and a dense population of APOD+ myCAFs within the tumor recovery zones." (PMID 40107247, 2025). "APOD has been identified as a part of the risk model in STAD and is relevant to tumor mutation burden and immune cell infiltration." (PMID 41438490, 2025). "In high-risk patients, APOD, OLR1, STC2, and DKK1 were found to be overexpressed, with APOD showing tumor-suppressive effects in certain cancers, while OLR1, STC2, and DKK1 are known to promote tumor growth and immune suppression." (PMID 39857718, 2025). "Collectively, these findings emphasize the critical roles of SELP+ HEVs and APOD+ myCAFs in facilitating T/NK cell infiltration and enhancing antigen presentation, thereby contributing to effective tumor regression." (PMID 40107247, 2025). "Serum levels of APOD peak when the tumor is benign but reduces with more invasive and metastatic forms of breast tumors." (PMID 38067270, 2023). "As such, it is suggested that a decrease in APOD levels increases tumor proliferation, as proven by its ability to suppress tumor growth in other cancers such as breast, prostate, and colorectal cancers." (PMID 38067270, 2023). "When apoD is present in cancer cells, it promotes the senescence of tumor cells and inhibits cell proliferation." (PMID 32306242, 2020). "We matched one control subject per case and assessed ApoD expression in the tumor cell nucleus and cytoplasm using tissue microarray immunohistochemistry." (PMID 28301514, 2017). "Among the seven potential footrot-associated proteins, haptoglobin precursor, afamin precursor, apolipoprotein-D have been reported as tumor biomarkers." (PMID 23418487, 2013). "Indeed, one of the described effects of ApoD is to induce senescence in the stroma, thus generating an environment favorable for tumor cell invasion." (PMID 39563861, 2024). "Strikingly, it showed that IGHG4 and IGKC were predominantly expressed in HER2neg TNBC group (in tumor tissues containing tumor cells and mesenchymal cells), whereas APOD and MUCL1 were highly expressed in HER2low group, which were consistent with the scRNA-seq data." (PMID 36998014, 2023). "However, there is no reasonable molecular mechanism revealing the secrets between B-Raf and tumor immune characteristics or the relationship among APOD, B-Raf, and the tumor immune microenvironment." (PMID 36713514, 2022). "APOD has been reported to exhibit tumor suppressive activity in some types of tumors." (PMID 34993138, 2021). "APOD may be a potential therapeutic target for tumor angiogenesis by suppressing PI3K-Akt-eNOS signaling, an essential pathway regulating angiogenesis." (PMID 34917513, 2021). "Therefore, the presence of apoD is at its highest in benign tumors, whereas its expression is at the lowest level in invasive cancer and BC with metastasis." (PMID 32306242, 2020). "ApoD, apoE and apoA-I in mammary tissues inhibit tumor growth." (PMID 32306242, 2020). "When these apolipoproteins, including apoD, apoE and apoA-I, are present in cancer tissues, they tend to inhibit tumor growth, and these apolipoproteins may be used in the clinic as therapeutic targets." (PMID 32306242, 2020).
tumor (continued). "Also, we identified NCAM1, CNTN1, SCG2, CADM1, IL-8, NPTX1, and APOD as PSCB in the tumor secretome." (PMID 31455042, 2019). "Hence, the findings suggest that APOD levels can be utilized as an early diagnostic marker for cancer initiation rather than a marker for tumor progression after initiation." (PMID 38067270, 2023). "Interestingly, APOD could bind to AA and change the end products of AA metabolism to reduce the activity of tumour cells." (PMID 36243728, 2022). "In spite of plausible biological hypotheses and the results of earlier studies, we did not observe an association between tumor ApoD expression and recurrence among ER+, tamoxifen-treated patients." (PMID 28301514, 2017). "Analysis of differential expression between GC tumor tissues and normal tissues revealed upregulated SERPINE1, IL1F10, IGFBP1, and ITIH2, whereas C6, GCG, GRP, and APOD were downregulated." (PMID 41551463, 2026). "RT-qPCR and Western blot analyses confirmed that CTHRC1, APOD, and S100A12 expression was significantly upregulated in the tumor group, while ASCL2 expression was significantly downregulated." (PMID 40898459, 2025). "The results showed that the expression levels of CTHRC1, APOD, and S100A12 in the tumor group were significantly upregulated, whereas the expression levels of ASCL2 in the tumor group were significantly downregulated." (PMID 40898459, 2025). "Reverse transcription quantitative polymerase chain reaction and Western blot analyses confirmed that CTHRC1, APOD, and S100A12 were significantly upregulated in the tumor group, whereas ASCL2 expression was significantly downregulated." (PMID 40898459, 2025). "SELP+ HEVs and APOD+ myCAFs foster favorable immunomodulatory stromal niches for improved outcomes, while STMN1+ cECs and MYF5+ MSCs form immunosuppressive niches in tumor invasion regions, highlighting therapeutic targets." (PMID 40107247, 2025). "This contrasts with healthy skin where APOD+ fibroblasts, RGS5+ and TAGLN+ pericytes populations largely colocalize, implying selective expansion of the RGS5+ pericytes during tumour angiogenesis." (PMID 38165934, 2024). "Five genes were subsequently selected by LASSO regression; CGB5, THPO, and PDGFRB were upregulated in the tumor tissue, while SLC10A2 and APOD were downregulated." (PMID 38228846, 2024). "Then, we verified the expressions of IGHG4, IGKC, APOD and MUCL1 at the protein level in tumor sections of clinical TNBC patients (HER2low, n = 5 vs. HER2neg, n = 5) by IF staining." (PMID 36998014, 2023). "The differential analysis also confirmed the high expression of CD74, HLA-DRA, C7, CCL12, and CCR3 in CAFs from P-LN but lower expression of VIM, APOD, MMP11, TAGLN, and CDKN2A compared with that in the primary tumor." (PMID 36569924, 2022). "The results showed that APOD, DCN, and PTN were downregulated in tumor samples compared with normal samples." (PMID 35420507, 2022). "We validated the transcriptional expression of identified 6 key fibrosis factors (PCOLCE2, APOD, APOE, TIMP1, HTRA3 and MT1A) in tumor and normal tissues obtained from 20 PTC patients." (PMID 36387901, 2022). "Based on the selection of APOD as a representative marker for the ASC population we rearranged the attractors of the PDAC tumor samples in terms of descending order of the rank of APOD from left to right." (PMID 34283835, 2021). "For the correlation between SLC22A17, APOD, and tumor drug resistance, we next determined the effect of SLC22A17 and APOD on drug sensitivity." (PMID 34306002, 2021). "We found that TENM1, FN1, and F12 are highly expressed in tumor tissue, while APOD and BTNL8 have a lower expression in tumor tissue." (PMID 34221185, 2021). "Tumor cells demonstrate strong positive staining for vimentin, CD34, apolipoprotein D, and nestin when subjected to immunohistochemical studies." (PMID 33715634, 2021).